CD4 (CD4 molecule)
Diseases named in the same sentence as CD4 in open-access papers (continued):
Sharing a sentence is not in itself a finding about the gene and the disease.
Sepsis (continued). "We hypothesize that the protective outcome of ghrelin in sepsis is mediated partially through the restoration of CD4 T cells’ proliferation." (PMID 30052667, 2018). "Thus, SPADE analysis also facilitates a more granular view into the functional derangements in CD4+ T cells observed in mice with pre-existing malignancy following sepsis." (PMID 29338031, 2018). "Thus, SPADE analysis facilitates a more granular view into the phenotypic derangements on CD4+ T cells observed in mice with pre-existing malignancy following sepsis." (PMID 29338031, 2018). "Besides lymphocyte apoptosis, decreased rate of CD4 T cell proliferation has been demonstrated in sepsis." (PMID 30052667, 2018). "In addition, we recently identified a cell-intrinsic role for 2B4 on CD4+ T cells in increasing immune dysfunction and mortality during sepsis." (PMID 29338031, 2018). "SIRT1 may also promote the repressor phenotype of CD4+Fox3p+ TReg cells, which are known to increase during sepsis." (PMID 30069485, 2018). "Studies in human septic patients show both CD4 T cells and B cells are reduced during the hyperinflammatory phase of sepsis, but there is limited data detailing the long-term impact of sepsis on these cells within the context of a CD4 T cell-dependent B cell response." (PMID 30429857, 2018). "However, there was a sepsis-related decrease in the number of CD4+ T cells in CD43-/- mice from sham controls and a trend towards a decrease in WT mice." (PMID 30226896, 2018). "Based on the known systemic immunologic changes that occur in cancer hosts, we hypothesized that the presence of pre-existing malignancy would result in phenotypic and functional changes in CD4+ T cell responses following sepsis." (PMID 29338031, 2018). "We demonstrated that blocking autophagy accelerated apoptosis and increased mortality in concordance with the insufficient autophagy process in CD4+ T cells in the murine sepsis model, suggesting that T cell autophagy plays a protective role against apoptosis and immunosuppression in sepsis." (PMID 27618275, 2017). "Thus, during polymicrobial sepsis, CD4+ pDCs are activated in the bone marrow and induce functional reprogramming of differentiating BMDC toward an immunosuppressive phenotype." (PMID 29218051, 2017). "Besides higher expression of BTLA in sepsis, Shubin and co-workers reported a higher proportion of CD4+ T cells expressing BTLA in patients who subsequently developed a nosocomial infection." (PMID 28056053, 2017). "Moreover, mice treated with the CXCR4 antagonist contained fewer PD-1+ LAG-3+ 2B4+ cells, suggesting that blockade of CXCR4 mitigates CD4+ T cell exhaustion during sepsis." (PMID 29232699, 2017). "The function of Mfn2 in CD4+ T cell apoptosis in sepsis is poorly understood." (PMID 29358849, 2017). "Peripheral blood from sepsis survivors was collected 5–10 months after sepsis diagnosis and analysed for the frequency, and the absolute number of CD4+Foxp3+ T cells and serum concentration of IL-33 and IL-10 together with age- and sex-matched healthy volunteer blood donors (n=14)." (PMID 28374774, 2017). "To get further insight into the expansion of CD11chiCD4+ pDCs (that we had previously termed “CD4+ DCs”) in the bone marrow during sepsis, we investigated the expression of CD4 and MHC class II on CD11chi and CD11cint pDCs among total CD11c+Bst2+Ly6C+B220+ pDCs (for gating)." (PMID 29218051, 2017). "While subversion of the CD4+ T cell response during commensalism might be of mutual benefit for C. albicans and the host, during invasive infection/sepsis blocking protective CD4+ T cell immunity might worsen clinical outcome." (PMID 28553273, 2017). "Therefore, to evaluate the relationship between Mfn2 expression, autophagy level, and apoptosis of CD4+ T cells in sepsis, we performed in vivo and in vitro investigations." (PMID 29358849, 2017). "Thus, the previously identified CD4+ DCs that expand in the bone marrow during sepsis are activated pDCs." (PMID 29218051, 2017).
Sepsis (continued). "However, an autophagy process in CD4+ T cells during sepsis was insufficient including the accumulation of p62." (PMID 27618275, 2017). "Thus, in sepsis, the increase in the proportion of Treg cells among the total number of T CD4+ lymphocytes is correlated with poor prognosis." (PMID 28770544, 2017). "Thus, CD4+ DCs accumulate in the bone marrow during sepsis and modulate the cytokine secretion pattern of subsequently differentiating BMDC toward increased IL-10 production." (PMID 29218051, 2017). "We demonstrated that blocking autophagy accelerated apoptosis and increased mortality in concordance with the insufficient autophagy process in CD4+ T cell in the septic murine model, suggesting that T cell autophagy plays a protective role against apoptosis and immunosuppression in sepsis." (PMID 27618275, 2017). "For instance, HIV-induced immune perturbations, low CD4/CD8 ratio and the residual immune dysregulation syndrome are some of the factors that had been described previously in the pathogenesis of HIV-associated sepsis." (PMID 27232185, 2016). "Furthermore, sepsis also remained a significant risk factor for LITB after controlling for viral load and CD4 counts in the regression models (p = 0.003)." (PMID 27232185, 2016). "The lower Treg percentages and higher CD4+ in the FO group may indicate that the sepsis-induced immunosuppression was mitigated, and the CD4+ cell population recovered when fish oil emulsion was administered." (PMID 26999192, 2016). "Interestingly, we observed that the percentage of BTLA+/CD4+T cells was significantly reduced in patients with severe sepsis or septic shock compared with healthy controls (all P <0.01)." (PMID 26329820, 2015). "However, there are conflicting reports on the level of BTLA expression on CD4+ T cells in healthy controls and patients with sepsis." (PMID 26329820, 2015). "Interestingly, they found that patients with sepsis had a significantly increased percentage of BLTA+CD4+ lymphocytes compared with patients with SIRS." (PMID 26329820, 2015). "Therefore, the percentage of BTLA+/CD4+T cells was a predictor of pejorative outcome in patients with sepsis as well." (PMID 26329820, 2015). "We suggest that CD4 cell counts are made for all HIV positives in future sepsis studies in Africa." (PMID 26670718, 2015). "Moreover, other classes of T lymphocytes (e.g. CD4 + CD25-) are reduced in sepsis, highlighting the need for additional studies in this area." (PMID 25887317, 2015). "Although a higher percentage of apoptotic cells among the CD8+ relative to CD4+ T lymphocytes had been already observed in previous studies in the context of sepsis and pulmonary disease, its significance in normal physiological conditions had never been discussed." (PMID 25880808, 2015). "Examination of PD-1 expression on CD4 and CD8 T cells showed that sepsis caused an increase in CD8 but not CD4 PD-1 expression compared to non-septic patients." (PMID 24387680, 2014). "This was associated with increased apoptosis of CD4+ and CD8+ cells after sepsis." (PMID 25029098, 2014). "A pilot study on monitoring activity of CD4+ T cells in sepsis was published in 2010." (PMID 25522739, 2014). "To determine whether autophagy in T cells contributes to survival in sepsis, we crossed Atg7f/f mice with mice expressing the T cell-specific Cre transgene (CD4-Cre mice)." (PMID 25029098, 2014). "CD4+ T-lymphocytes, a population of special relevance for acute survival in sepsis according to some but not all studies was particularly vulnerable to apoptotic death in polymicrobial sepsis models." (PMID 25541945, 2014). "Available evidence on the role of CD4+ T-cells for onset and resolution of sepsis is controversial." (PMID 25541945, 2014).
Sepsis (continued). "In our study, ex vivo PHA-induced production of both pro- and antiinflammatory cytokines from isolated CD4+ T cells was decreased in sepsis patients compared with healthy controls and was lowest in children with sepsis who developed persistent or nosocomial infection." (PMID 25005517, 2014). "To further study whether autophagy is involved in apoptosis during sepsis, we evaluated the time-course of autophagy and apoptosis in CD4+CD8− and CD4−CD8+ splenic T cells after CLP." (PMID 25029098, 2014). "Potential mechanisms of immunosuppression in sepsis include T-cell exhaustion, apoptotic depletion of CD4 and CD8 T-cells, myeloid-derived suppressor cells, and increased T-regulatory cells, all of which might contribute to viral reactivation." (PMID 24919177, 2014). "It needs to be determined whether ATP_CD4 concentration changes very early, for instance before sepsis can even be diagnosed." (PMID 25522739, 2014). "Under present support systems and treatment guidelines, total CD4+ cell counts play a role influencing the mortality of sepsis patients and a trend toward to Th1 differentiation might help patients with severe sepsis to survive." (PMID 23670410, 2013). "The association of circulatory Th17 and Treg lymphocytes with mortality in severe sepsis may be due to the change in total CD4+ T lymphocytes." (PMID 23670410, 2013). "Based on these results, and the results from our previous study whereby we found that BTLA gene-deficient mice were protected from experimental septic morbidity and mortality, we evaluated the effects of BTLA on CD4+ T cells following experimental sepsis induction in mice." (PMID 24289156, 2013). "The ratio of CD4+/CD8+ is another parameter to evaluate immunological status in sepsis." (PMID 23327199, 2013). "Since CEACAM1 generally functions as an inhibitor of T-cell receptor activation, increased CD4+ T-cells CEACAM1 expression in sepsis may contribute to the suppression of T cell functions as observed in sepsis." (PMID 23894299, 2013). "It is reported that polymicrobial sepsis increases the number of splenic CD4+CD25+ Tregs after CLP." (PMID 22590504, 2012). "We found that patients with sepsis did have a higher expression of CD69 on CD4+ T cells at the onset of sepsis, as well as a higher circulating percentage of CD69 expressing CD4+ T cells and this did not significantly change over the course of the acute illness (data not shown)." (PMID 22742734, 2012). "Given the association between certain HIV-1 subtypes and rate of CD4 decline and mortality, we sought to determine HIV-1 subtype distribution and mortality in a cohort of predominantly HIV-infected patients with severe sepsis in Uganda." (PMID 23144755, 2012). "The factors associated with hospital mortality in univariable analysis were CD4 lymphocyte count (per 10 cells/mm3 decrease), admission diagnosis of sepsis, the interval between hospitalization and ICU transfer of more than 24 hours, and serum albumin level (per 1 g/dl decrease)." (PMID 21871086, 2011). "In post-septic patients, the ratio of IFN-γ to IL-4 producing peripheral blood CD4+ T cells appears skewed towards IL-4, and the maintenance of TH1 T cells following sepsis appears to be negatively affected by a unique susceptibility to apoptosis and activation-induced cell death." (PMID 21655295, 2011). "Similarly, the mean CD4+ lymphocyte ATP content from our sepsis survivors is similar to the reported mean CD4+ lymphocyte ATP content of healthy controls (431 vs. 432, respectively)." (PMID 20540723, 2010). "Whether CD4+CD25+ Tregs participate directly in sepsis-induced immunoparalysis resulting in poor outcomes remains to be investigated." (PMID 20064232, 2010). "In one study, patients with S. aureus and S. pneumoniae sepsis showed significantly decreased numbers of CD4+ and CD8+ T cells, and NK cells while in another, patients with MRSA superantigen-associated glomerulonephritis showed increased numbers of DR+ CD4+ and CD8+ T cells and NK cells." (PMID 19424507, 2009).
Sepsis (continued). "Recently, a subset of CD4+ T cells possessing both T helper 1 (Th1) and regulatory T cell (Treg) phenotypes, termed Th1-Treg cells, has been identified; however, their function in sepsis remains unknown." (PMID 41892312, 2026). "Furthermore, while the expansion of CD69+ naïve CD4+ T cells in sepsis is interesting, it may reflect cohort-specific factors and requires validation in larger, independent cohorts." (PMID 41208955, 2025). "Integrating the recently proposed concept of PANoptosis and the concurrent existence of multiple interconnected PCD modes in immune cells, we hypothesize that NUFIP1-mediated ribophagy might play a regulatory role in PANoptosis of CD4+ T lymphocytes during sepsis." (PMID 40995563, 2025). "There were less IL-10 producing CD4+ T cells in sepsis patients and the ones that were present were less able to respond to ex vivo stimulation than their healthy counterparts, which is somewhat congruent with other sepsis observations of a regulatory T cell compartment failure." (PMID 39935482, 2025). "We found that the levels of NUFIP1 and ZBP1 in the CD4+ T lymphocytes of septic patients significantly increased compared to those without sepsis, corresponding to experimental data in murine models, thereby underscoring their conserved biomarker potential for the diagnosis of sepsis." (PMID 40995563, 2025). "Concurrently, BLOC1S1 exhibited the strongest negative correlation with central memory CD4+ T cells (cor = −0.761, P < 0.001), indicating that BLOC1S1 might suppress the function or quantity of central memory CD4+ T cells, playing a complex role in the immunological dysregulation of sepsis." (PMID 40370519, 2025). "Therefore, using rapamycin to modulate the mTOR signaling pathway could regulate the onset of ERS-induced cell apoptosis through autophagy and ultimately reverse the fate of CD4+ T cells in elderly sepsis." (PMID 40933998, 2025). "However, in our study, the differential expression analysis suggests that although sepsis samples maintained increased proportions of effector CD4+ T cell populations, these populations displayed a complex impaired expression profile compared to control populations." (PMID 41208955, 2025). "Moreover, autophagy dysfunction triggers CD4+ T-cell apoptosis in sepsis." (PMID 40028203, 2025). "Additionally, MMP9 induced increased PD-1 expression on CD4+ T cells and reduced IL-2 and IFN-γ production upon anti-CD3/CD28 stimulation, confirming the association between MMP9 and CD4+ T cell exhaustion during sepsis." (PMID 41306770, 2025). "In summary, we speculate that the decreased expression of LGALS9 in sepsis patients may enhance the activation and differentiation of CD4+‐naive T cells, leading to their differentiation into regulatory T cells with stronger immune response capabilities during inflammation." (PMID 39044269, 2024). "Previous studies showed that recurrent sepsis or post-sepsis state could induce the exhaustion and impaired response of CD4+ T cell and memory CD8+ T cell, along with the increase of regulatory T cells and myeloid derived suppressor cells that had T cell inhibiting capabilities." (PMID 38350868, 2024). "Thus, in the previously published study we surmised that CD4+ Foxp3+ IL-10-producing cells could be mechanistically responsible for the observed increase in sepsis survival in CD28 agonist-treated animals." (PMID 38633258, 2024). "As an important immune cell, CD4+ T cells may play a significant role during sepsis." (PMID 39290582, 2024). "First, although the correlation between CTLA-4 expression on CD4+ lymphocytes and immunosuppression, and the association between CTLA-4 expression and autophagic–lysosomal disorders, were identified among a large sample of patients with sepsis, this study was purely a clinical study." (PMID 39104530, 2024). "It remains contentious whether CD4+ T cells are intimately involved in the early stages of sepsis." (PMID 39290582, 2024).
Sepsis (continued). "The compromised ability of CD4+ T cells to coordinate immune responses and communicate with other immune cells could contribute to inadequate pathogen clearance and immune dysregulation, thereby impacting the severity and outcome of sepsis survivors." (PMID 39691721, 2024). "The findings above imply that CTLA4 accumulation is accompanied by impaired autophagy and increased mTOR signaling pathway activity, there may be a regulatory link between mTOR, autophagy, and CTLA4 accumulation that impacts CD4+ T cell manifestation in sepsis." (PMID 39104632, 2024). "This is consistent with our observation of a higher frequency of infection in the BPD infants, including sepsis and pneumonia, and also with an adaptive immune response as indicated by apparent shifts from naïve to memory among B cells, CD4 T cells and CD8 T cells." (PMID 37507442, 2023). "In addition, TEM results showed that splenic CD4+ T lymphocytes in sepsis exhibited notable formation of autophagosomes containing copious ribosomes to be degraded and swelling of the ER, which further confirmed the conspicuous phenomenon of ribophagy in T lymphocytes induced by septic challenge." (PMID 36873287, 2023). "Therefore, CD4+ T-cell-derived EVs might place unique demands on the DGK/DAG/PKC/NOX4 pathway to promote sepsis-induced lung injury in mice, including oxidative stress and inflammation." (PMID 36959535, 2023). "However, the number of CD4++CD25+CD127-/low Treg decreased during sepsis (P<0,01**)." (PMID 38094297, 2023). "Furthermore, CD4 and STAT4 had higher degrees in the PPI network and have been reported participate in immune mechanisms underlying sepsis, which indicated their important regulate roles in sepsis immune processes." (PMID 37620751, 2023). "In conclusion, this study found that most sepsis patients might have decreased CD3+, CD4+, and CD8+ T lymphocyte counts in the early stages, and the decrease in CD3+ T lymphocytes and the decline in the CD4+/CD8+ ratio are correlated with the poor prognosis of sepsis patients." (PMID 38170088, 2023). "In addition to impaired production of effector molecules, sepsis patients of all age groups present with severe apoptotic depletion of CD4+ and CD8+ T cells, B cells, and dendritic cells, which results in lymphopenia and is associated with sepsis severity and mortality." (PMID 37109229, 2023). "In addition, CD4 Th1 T cell abundance was negatively correlated with the insulin signaling pathway (R = -0.72, P < 0.01), with the highest negative correlation, and this pathway was down-regulated in sepsis patients." (PMID 37077915, 2023). "Thus, sepsis-induced mregDCs might exert dual immunoregulatory and immune stimulatory functions on CD4+ T cell responses." (PMID 35832091, 2022). "However, in a few studies researchers have examined the role and associated mechanisms of Nrp‐1 in immunosuppression and whether it affects the cell viability of CD4+CD25+ Tregs in sepsis." (PMID 34758202, 2022). "However, during sepsis this mechanism is insufficient, so the blockade of T cell autophagy accelerates apoptosis; consequently, the increased expression of IL-10 by CD4+ T cells might promote a further immunosuppressive state." (PMID 35054993, 2022). "Our results provide evidence showing that recurrent sepsis exacerbates CD4+ T cell exhaustion and decreases antiviral immune responses, contributing to significant morbidity, increased late mortality, and increased health care burden in recurrent sepsis patients." (PMID 33717146, 2021). "Lymphopenia is a hallmark of sepsis, and profound apoptosis‐induced depletion of lymphocytes including CD4+ and CD8+ T cells, B cells, and natural killer cells demonstrates extensive loss of lymphocytes in spleens, intestines, and other organs in patients who died of sepsis." (PMID 33378581, 2021). "However, whether IL-9-producing CD4(+) T cells and IL-9 have protective effects in sepsis need confirmation by more studies." (PMID 33941281, 2021).